RNVU1-30 (RNA, variant U1 small nuclear 30)
Gene: Small nuclear RNA gene on chromosome 1 (149,636,766 to 149,636,929, forward strand). Ensembl gene ENSG00000206828.
Gene Ontology:
Molecular function: pre-mRNA 5'-splice site binding
Biological process: mRNA 5'-splice site recognition
Cellular component: U1 snRNP
Homologues: Orthologues: dog U1 (70% identical), rabbit U1 (62% identical). Paralogues in human: RNVU1-4 (96% identical), RNVU1-3 (91% identical), RNVU1-7 (80% identical), RNU1-1 (79% identical), RNU1-2 (79% identical), RNU1-27P (79% identical), RNU1-28P (79% identical), RNU1-3 (79% identical), RNU1-4 (79% identical), RNU1-67P (79% identical), RNVU1-18 (79% identical), RNVU1-29 (79% identical), and 134 more.